RNU6-225P (RNA, U6 small nuclear 225, pseudogene)
Gene: Small nuclear RNA gene on chromosome 22 (20,416,797 to 20,416,899, reverse strand). Ensembl gene ENSG00000207343.
Homologues: Orthologues: macaque U6 (85% identical). Paralogues in human: RNU6-1 (90% identical), RNU6-2 (90% identical), RNU6-3P (90% identical), RNU6-4P (90% identical), RNU6-5P (90% identical), RNU6-6P (90% identical), RNU6-9 (90% identical), RNU6-10P (89% identical), RNU6-12P (89% identical), RNU6-13P (89% identical), RNU6-16P (89% identical), RNU6-17P (89% identical), and 1288 more.